CD46 (CD46 molecule)
Diseases named in the same sentence as CD46 in open-access papers (continued):
Sharing a sentence is not in itself a finding about the gene and the disease.
tumor (continued). "The Ad11p virus offers several advantages within the context of improved delivery to tumours, including the use of CD46 and desmoglein-2 as primary receptors, rapid release from a cell, and lower seroprevalence." (PMID 30956777, 2019). "High expression of the mCRPs membrane cofactor protein (CD46), decay-accelerating factor (CD55), and CD59 (protectin) on tumor cells is associated with increased metastatic potential, and poor prognosis in a range of tumors." (PMID 31001273, 2019). "The knob region is essential for the interaction of the virus with host cells, where it is a ligand of the membrane protein CD46, which is frequently overexpressed in tumor cells." (PMID 29662661, 2018). "Immunohistochemistry of excised tumours showed that human CD46 staining is confined to the cellular membrane in both HCT116 and CT26-CD46 tumours." (PMID 29898782, 2018). "CD46 levels vary throughout CT26-CD46 allografts, suggesting expansion of cells with differing levels of CD46 during tumour implantation." (PMID 29898782, 2018). "Compared with the vehicle-transfected group, Ad5/35-tk/GCV inhibited the tumor growth of CD46-overexpressing cells, but revealed reduced tumor cytotoxicity in CD46-suppressed cells (p = 0.005 by a repeated-measures ANOVA)." (PMID 30201920, 2018). "Following Ad5/35-tk/GCV treatment, the average tumor volume was 48.55 ± 27.43 mm3 in the CD46-overexpressing group, 881.57 ± 141.72 mm3 in the CD46-reduced group, and 550.93 ± 74.39 mm3 in the vehicle group." (PMID 30201920, 2018). "Expression of human CD46 in this allograft 23 days post- tumour inoculation suggests low immunogenicity of CD46 in mice and validates the use of CD46-expressing mouse cell lines to study virus uptake and early virus transduction in mouse cells." (PMID 29898782, 2018). "The CAR receptor is rarely expressed in tumours and so adenovirus is often engineered to express differing capsid and fibre proteins (pseudotyping), facilitating entry through receptors such as CD46 that are abundant in tumours." (PMID 30103501, 2018). "Expression of human CD46 in HCT116 tumours in a xenograft model was ubiquitous, except for mouse stromal and endothelial tissue." (PMID 29898782, 2018). "In mice, modulating intrinsic C3 activity (the equivalent of C3b-mediated CD46 engagement in humans) in tumor-infiltrating lymphocytes can promote tumor progression." (PMID 30305631, 2018). "The attenuated Edmonston strain is used for oncolytic virotherapy given its proven safety profile and also natural tumor specificity due to the upregulation of CD46 on tumor cell surface that the virus uses for cellular uptake." (PMID 28884088, 2017). "While the elevated levels of CD46 can enhance the malignant phenotype in cancer it also engenders the tumor cells more sensitive to infection by MV-Edm potentiating cell killing." (PMID 28968974, 2017). "Supposedly, selectivity for tumor cells is on one hand due to overexpression of CD46, one of the receptors used by attenuated MV strains." (PMID 28695108, 2017). "All cultures were characterized for tumor surface or stem-like marker expression, namely CD46, CD47, CD55, CD56, CD63, CD90, and CD99." (PMID 28545562, 2017). "In relation to MV-mediated oncolysis, the frequent overexpression of CD46 on many tumour cell types to escape autologous complement-dependent cytotoxicity accounts for some of the selectivity of attenuated MV replication in transformed cells." (PMID 27782084, 2016). "Many tumors express increased CD46 levels on their surface, and anti-tumor activity of Edmonston MeV has been shown in several mouse xenograft models for lymphoma, multiple myeloma, glioma, ovarian, colorectal, breast, and liver cancers." (PMID 27657109, 2016). "In order to profile the expression level of CD46 in human cancers, tumor tissue microarray slides were stained with anti-CD46 antibodies." (PMID 27203670, 2016).
tumor (continued). "Considering that the actual tumor cells represent only a small fraction within the tumor microarray, CD46 was quite highly expressed in both PCa and CRC." (PMID 27203670, 2016). "In tumor tissues, CD46 was most prevalently expressed in cancers of the colon and prostate, in which more than 35 % of the tumors overexpressed CD46, while CD46 expression was less than 11% in other tumors." (PMID 27203670, 2016). "In contrast, while CD46 is expressed more strongly in tumor cells than other cell types, it is expressed ubiquitously in all nucleated human cells." (PMID 26317644, 2015). "CD46 is often overexpressed on tumor cells of many cancer types to escape complement-mediated cytotoxicity." (PMID 26539644, 2015). "Ubiquitous distributions of CD46 molecules among normal tissues however need an additional system to secure tumor specificity in AdF35-mediated transduction." (PMID 26059686, 2015). "The unmodified live attenuated EdMV strain has potent antitumor activity but lacks tumor specificity due to its native receptor-specificity to CD46 and SLAM." (PMID 24921409, 2014). "Taking into account the usage of CD46 and nectin-4 as viral entry ports and their frequent presence and overexpression on different tumor cells, MV vaccine strains are regarded as potential oncotropic and oncolytic agents." (PMID 24921409, 2014). "Here, we also found that the levels of CD46 expression in HCC tissues were significantly higher than those in other types of tumor tissues and in the adjacent normal tissues." (PMID 24297460, 2014). "Given the restricted PVRL4 distribution to most human body tissues compared to the ubiquitous CD46 expression and the presence of SLAM on activated lymphocytes and dendritic cells, PVRL4 is a promising tumor-associated marker for cancer therapy." (PMID 24892636, 2014). "The levels of CD46 expression in HCC tissues were significantly higher than those in the other tumor tissues and the adjacent normal tissues." (PMID 24297460, 2014). "By contrast, CD46, a cellular receptor for Ad11 (subgroup B), is highly expressed in various types of malignant tumor cells including HCC cells." (PMID 23292657, 2013). "Despite recent advances in the identification of MV cellular receptors, CD46 is still considered to be critical in determining the sensitivity of tumor cells to oncolytic strains of MV." (PMID 23586034, 2013). "As derivatives of the Edmonston vaccine strain, these viruses display a natural tropism for the CD46 membrane protein, an inhibitory complement regulator strongly over-expressed by many types of tumor relative to normal tissue." (PMID 23134812, 2012). "Natural tumor tropism as cellular receptor for entry CD46 is expressed on tumor cells.Good safety records as included in vaccine schedule of canines." (PMID 22216938, 2012). "In contrast, most subgroup B Ads bind to CD46, a receptor often upregulated in a number of tumor types, including breast, cervical, liver, lung, endometrial and hematological malignancies." (PMID 20543907, 2010). "In contrast, tumor cell surface expression of CD46, the putative ColoAd1 receptor, appears to increase with stage and grade in a variety of cancers." (PMID 18560559, 2008). "Furthermore, the CD46 pathway, which is linked to immunosuppression, showed stronger interactions between APOE‐negative tumour cells and immune cells, particularly at the lymph node metastasis site." (PMID 39810624, 2025). "Alternatively, AdVs that engage CD46 may exploit its high expression on tumor cells, thereby enhancing therapeutic specificity and efficacy." (PMID 40309774, 2025). "Furthermore, MV-Edm is able to distinguish between high CD46 densities typical of tumor cells and lower CD46 densities characteristic of normal cells to promote the preferential killing of tumor cells." (PMID 40309774, 2025). "Interestingly, it has recently been found that CD46 plays a pivotal role in tumor growth and metastasis." (PMID 38919630, 2024).
tumor (continued). "Similarly, measles virus exploits its receptors CD150 and CD46 on tumor cells to trigger the immune response, leading to increased IFNγ levels and a favorable immune milieu for tumor clearance." (PMID 38731910, 2024). "CD46 is a membrane protein involved in the regulation of complement deposition, ubiquitously expressed on nucleated cells, and its expression is upregulated in many tumour types." (PMID 38037840, 2024). "Interestingly, retargeting of HAdV‐C5 to CD46 has previously demonstrated to enhance anti‐tumour efficacy compared to wildtype virus despite comparable protein expression of CAR and CD46 in the tumour." (PMID 38037840, 2024). "Furthermore, CD46 molecules playing the role of the receptor for attenuated strains of MV are known to be upregulated on the surface of tumor cells." (PMID 36366531, 2022). "All GBM cell lines tested expressed CD46, as did non-tumor cell lines." (PMID 36366531, 2022). "Furthermore, the hyperexpression of the CD46 on the surface of tumor cells allows the MV to selectively infect and lyse the tumor." (PMID 36366531, 2022). "Subcutaneously injected B16-CD46 cells formed tumors; however, CD46 expression was severely reduced in resected tumors at day 17, which may be due to increased immunogenicity of the CD46+ clones, as human CD46 may serve as a tumor antigen in this model." (PMID 35141399, 2022). "In line with the comparable efficacy of UV-inactivated virus, viral gene expression, replication, and cytotoxicity are likely limited by post-entry restriction factors in the B16 model despite ectopic CD46 expression allowing for viral entry into the tumor cells." (PMID 33863363, 2021). "Second CD46 is commonly overexpressed on a variety of tumor cells." (PMID 33147799, 2020). "Based on these observations, CD46 could be included in a list of biomarkers to predict potential tumor response to virotherapy by attenuated MV." (PMID 33291506, 2020). "Moreover, a great deal of data showed that mCRP expression, contains CD46, CD55, and CD59, are linked to worse clinical outcomes, and in some cases highly specific for tumor cells, many approaches to block mCRP expression on tumor cells have been studied." (PMID 33614473, 2020). "CD46 is highly overexpressed on a variety of human tumor cells." (PMID 33147799, 2020). "Furthermore, the downregulation of the complement inhibitor Crry (the murine counterpart of CD46) on tumor cells in a mouse model of metastatic bladder cancer induced a protective anti-tumor CD8+ T cell response." (PMID 33147799, 2020). "This amplification correlates with markedly increased expression of CD46 by the tumor." (PMID 33147799, 2020). "On the other hand, the naked MV-Edm could enter numerous types of tumor cells via the ubiquitously expressed protein CD46." (PMID 31533779, 2019). "Together this data indicates the intricate role of CD28 in regulating CD46, and the important cytokine-related role that these two may play in tumor specific adaptive responses." (PMID 31164885, 2019). "To exclude that CD46 overexpression or suppression itself resulted in cell growth rate changes, we performed an in vitro cell proliferation assay, which revealed that all three EJ tumor types had similar proliferation rates." (PMID 30201920, 2018). "CD46 has been shown to be overexpressed in many primary cancers, as well as in tumor cell lines." (PMID 30201920, 2018). "While CAR expression was not correlated with disease progression, CD46 expression was inversely correlated with tumor grade, stage, and risk grade." (PMID 30201920, 2018). "In contrast, Ad5/35-tk/GCV affected tumor growth depending on the CD46 expression status." (PMID 30201920, 2018). "Likewise, in a tumor xenograft model in nude mice that was induced with cells manipulated to express different CD46 levels, there was a tight inverse correlation between CD46 expression and tumor growth following Ad5/35-tk treatment in combination with GCV." (PMID 30201920, 2018).
tumor (continued). "In this study, we showed that CD46 expression levels varied considerably among 59 tumor biopsies." (PMID 30201920, 2018). "CD59 and CD46, also highly expressed in IH, prevent complement-mediated tumor cell lysis." (PMID 27786256, 2016). "Our tumor microarray data also showed that a low level of CD46 expression in normal liver which may imply that adenoviral targeting of CD46 may results in liver toxicity." (PMID 27203670, 2016). "When CD46 expression of score 2-3 was arbitrarily set as positive expression, CD46 expression was positively correlated with differentiation (p=0.041) and negatively correlated with perineural invasion (p=0.038), tumor stage (p=0.003), and distant metastasis (p=0.001)." (PMID 27203670, 2016). "Therefore, group B Ads are attractive gene therapy vectors since they can overcome the limitations in tumor transduction efficacy through utilizing more ubiquitously expressed CD46." (PMID 27203670, 2016). "However, because CD46 is ubiquitously expressed, side effects and/or inefficient targeting to tumor cells remains to be considered." (PMID 26317644, 2015). "This demonstrates that CD46 is required for MV infection of MPM tumor cells." (PMID 26539644, 2015). "However, the proper assessment of tumor targeting with these chimeras will require DSG2 or CD46 transgenic mice." (PMID 28548059, 2014). "As expected, a majority of efficiently infected tumor cells exhibited a high CD46 surface level." (PMID 23586034, 2013). "By contrast, CD46 is highly expressed in various types of malignant tumor cells." (PMID 23292657, 2013). "Theoretically, CD46 screening of tumor tissue could help guide physicians to identify which patients should be treated with this agent." (PMID 22312363, 2012). "This suggests that CD46 expression may be a contributing factor to the observed tumor selectivity of ColoAd1." (PMID 22312363, 2012). "Recently, it has been demonstrated that chimeric Ad5 vector possessing fiber proteins derived from group B adenoviruses such as Ad35, Ad11 can efficiently enter tumor cells that are refractory to Ad 5 infection by utilizing CD46 as a high-affinity primary attachment receptor." (PMID 22266706, 2012). "It is possible that Ad11 could infect a wider range of tumor cells and overcome receptor downregulation; the latter is a known problem with Ad35 and CD46." (PMID 20543907, 2010). "This suggests that CD46 expression may be a contributing factor to the observed tumor selectivity of ColoAd1 and thus may be a potential tool for pre-screening patients for treatment with this therapeutic agent." (PMID 18560559, 2008). "Thus, increased CD46 expression on malignant cells could be considered an immune evasion mechanism to prevent complement activation to benefit the tumor cell." (PMID 40309774, 2025). "The complement binding assay results showed that the shRNA group’s cell survival rate was significantly lower than that of the SC-shRNA group, indicating that CD46 could inhibit complement activation, protect tumor cells from complement cleavage and promote tumor escape." (PMID 40475017, 2025). "However, targeting CD46 on tumor cells may encounter limitations, as this molecule is expressed in most normal human cells." (PMID 39342391, 2024). "In addition, CD46 expression is up-regulated on malignant tumor cells." (PMID 37856461, 2023). "Typically, the high density of CD46 on tumor cells contributes to extensive cell fusion and enhancement of viral gene expression and provides a compelling explanation for the oncolytic specificity of the MV–Edmonston strain and its favorable use for CD46-targeted cancer therapy." (PMID 34696358, 2021). "Therefore, although increased CD46 on tumor cells is generally considered an immune evasion mechanism, in certain situations, preventing complement activation may also benefit the host." (PMID 33147799, 2020).
tumor (continued). "Although heterogeneous relative to tumor type, complement proteins expressed by malignant cells are variable; in general, tumor cells express low C8 and C9 but highly express C3 and the regulators factor H, factor I and especially the membrane regulators CD46, CD55 and CD59." (PMID 33147799, 2020). "Together this data suggests a temporally and spatially regulated role of CD46 in adaptive immune responses, which also serves as an important indication that the complement cascade is capable of exerting a driving influence on adaptive T cell responses during anti-tumor responses." (PMID 31164885, 2019). "Overexpression of the measles virus (MV) receptor CD46 in many tumour cells may direct the virus to preferentially enter transformed cells and there is increasing awareness of the importance of nectin-4 and signaling lymphocytic activation molecule (SLAM) in oncolysis." (PMID 27782084, 2016). "However, targeting CD46 on tumor cells may be somewhat limited, since most normal human cells express this molecule on their surface." (PMID 27657109, 2016). "They then observed that the three insensitive cell lines express on their surface a lower level of CD46 molecules compared to the five sensitive cell lines, a result compatible with the accepted view that the oncolytic activity of MV depends on overexpression of CD46 by tumor cells." (PMID 26539644, 2015). "Cell-cell interaction analysis demonstrated strong communication between CGR11-high tumor cells and immune components (TAMs, TECs, T cells) via ligand-receptor pairs such as CD6, CD46, MIF, VEGF, and TRAIL." (PMID 41573680, 2025). "We found that TGFB1/EGFR, LTA/LTBR, CD46/JAG1, and AREG/EGFR ligand‐receptor pairs were stronger in CD4+ T cell‐Plac1+ tumor cells than in CD4+ T cell‐Plac1− tumor cells, among which LTA/LTBR expression was highly specific for Tregs and Plac1+ cells." (PMID 40056047, 2025). "This indicates that CD46 and TREM1 promote tumor proliferation and metastasis by inhibiting autophagy and apoptosis during OSCC development." (PMID 40475017, 2025). "As a complement regulatory protein, CD46 prevents complement membrane attack complex (MAC) formation by degrading C3b/C4b, thereby protecting tumor cells from complement-mediated lysis." (PMID 41415031, 2025). "Tumor cells often overexpress membrane complement regulatory proteins (mCRPs) such as CD55, CD46, and CD59, which inhibit complement activation and protect against complement-mediated cytotoxicity." (PMID 40806542, 2025). "This antibody bound the same epitope on CD46 recognized by UA20, internalized via macropinocytosis (a relatively tumor-specific uptake mechanism), and demonstrated favorable developability for clinical translation." (PMID 40309774, 2025). "Studies have shown that CD46 and TREM1 are highly expressed on the surface of a variety of tumor cells throughout the body." (PMID 40475017, 2025). "MV targets tumor cells through various receptors, including lymphocyte activation molecule 150 (CD150), lymphocyte activation molecule 46 (CD46), and Nectin cell adhesion molecule 4 (NECTIN-4)." (PMID 39697335, 2024). "Tumor cells express membrane-bound complement regulatory proteins (mCRP; CD35, CD46, CD55, and CD59) that normal cells use to prevent excessive activation of complement cascades in the early stages of an immune response." (PMID 39125875, 2024). "Our results revealed the main outgoing signals of FDX1 + tumor/epithelial cells were PDGF, WNT, CD46, MHC-1, MIF, and MK pathways, while the primary incoming signals were IFN-II and other pathways." (PMID 38200479, 2024). "YS5, the human antibody that we developed and used to construct the CD46 targeting ADC (FOR46) that is in multiple clinical trials, binds to a tumor selective conformational epitope, enabling therapeutic targeting of CD46." (PMID 36906664, 2023).